NRAS (NRAS proto-oncogene, GTPase)
Diseases named in the same sentence as NRAS in open-access papers (continued):
Sharing a sentence is not in itself a finding about the gene and the disease.
cancer (continued). "Given that KRAS is predominantly mutated in cancers harboring RAS mutations, drug development targeting NRAS mutations lags far behind and remains an unmet medical need." (PMID 37083947, 2023). "A significantly greater proportion of HRAS-mutant cancers (48.4%) were found to have co-altered mutations along the RTK/MAPK/PI3K pathways compared to KRAS- (41.4%) and NRAS-mutant (38.4%) cancers (p<0.05 for both)." (PMID 37503077, 2023). "Although the exact regulation of miR-708 on the NRAS signaling pathway remains inconclusive, we believe that there is an opportunity for miR-708 to cooperate with ERKi and AKTi to tackle NRAS mutant cancer effectively." (PMID 37083947, 2023). "This study presents the possibility for targeting RAS-driven cancers by specifically blocking NRAS palmitoylation." (PMID 37317974, 2023). "The receptor tyrosine kinase/RAS/MAP kinase (MAPK) pathway is an oncogenic pathway with widespread aberrancies in human cancers; indeed, 20%-30% of cancer patients harbor RAS (KRAS, HRAS, or NRAS) mutations." (PMID 37705755, 2023). "This suggests that rare codon-mediated limitation of Ras protein expression is not responsible for the much higher representation of mutants of KRAS than NRAS in human cancer patients." (PMID 36864243, 2023). "We focused on GDSC data on NRAS-mutant pan-cancer cell lines, to pinpoint key signaling targets in direct or indirect associations with NRAS, in order to identify other druggable targets involved in drug resistance." (PMID 35534592, 2022). "Presently, although there are fewer studies on human cancers caused by mutations of NRAS than on those induced by mutations of KRAS, it is known that mutationsof NRAS are indeed involved in human tumorigenesis." (PMID 36080363, 2022). "We selected the drug-sensitive (IC50 < -1) and -resistant (IC50 > 1) NRAS-mutant cancer cell lines based on IC50 value and color intensity and enlisted these." (PMID 35534592, 2022). "Across cancers, NRAS G13 was twice as frequent as G1229, while NRAS G12 and G13 were both observed at 10% in RRMM." (PMID 35768438, 2022). "It was observed that 41 NRAS-mutant cancer cell lines were commonly responsive to 10 drugs, namely PD-0325901, Trametinib, Selumetinib, TL-1-85, CI-1040, NG-25, PLX4720, AP-24534 (Ponatinib), Xl-184 (Cabozantinib) and Foretinib." (PMID 35534592, 2022). "In parallel to our studies with mutant KRAS, we set out to identify a role for AGO2 in mutant HRAS and NRAS-driven cancers." (PMID 35923912, 2022). "Nearly all factors of the RAS pathway are altered in cancer, most frequently activating mutations of KRAS, NRAS, HRAS, BRAF and receptor tyrosine kinases (RTKs)." (PMID 35456940, 2022). "NRAS codon distribution more closely resembled the pan-cancer assessment, with Q61 as the dominant codon observed in 73% of cases, and non-G12/G13/Q61 codons in 7% (middle)." (PMID 35768438, 2022). "KRAS, HRAS and NRAS, the three subsets of RAS, are well known to be activated by mutation in nearly a quarter of all human cancers, of which KRAS plays a key role in driving tumorigenesis." (PMID 35422066, 2022). "It is also worth noting that there are a number of members of the Ras subfamily of GTPases which are frequently mutated in human cancers, including HRAS, NRAS and most commonly, KRAS, with activating Ras mutations found in ∼20% of cancer patients." (PMID 35119068, 2022). "High basal levels of autophagy are characteristic of several cancers with mutations in RAS proteins, such as H1299 (with mutant NRAS proteins) and A549 (with mutant KRAS proteins) cells." (PMID 35740374, 2022). "These somatic mutations are missense and affect residues homologous to the cancer‐associated ones mutated in HRAS, KRAS and NRAS." (PMID 36394128, 2022).
cancer (continued). "Using several cellular models of mutant HRAS and NRAS-driven cancers, this study evaluated the interaction of AGO2 with these RAS isoforms and elucidated the functional implications of this interaction." (PMID 35923912, 2022). "NRAS, along with KRAS and HRAS, constitutes the RAS family, which is the most frequently mutated gene family in cancer." (PMID 36003381, 2022). "Four RAS proteins from this superfamily (HRAS, NRAS, KRAS4A, and KRAS4B), encoded by three RAS genes (HRAS, NRAS, and KRAS), are commonly mutated in and drive the initiation and progression of several human cancers." (PMID 35839996, 2022). "MD Anderson Cancer Center in Texas published their Arab patients’ data describing that KRAS/NRAS/BRAF prevalence were 44.4%, 4%, and 4%, respectively, compared to 48.4%, 4%, and 4%, respectively, in the matched Western population." (PMID 35619874, 2022). "Mutant NRAS is an intractable target indirectly and frequently involved in drug resistance in multiple cancer types." (PMID 35534592, 2022). "Mutations in HRAS and NRAS account for approximately 4% and 11% of all RAS-driven cancers, respectively." (PMID 35923912, 2022). "KRAS, NRAS and BRAF mutations were frequently identified in high cancer cell fractions and considered driver mutations in MM." (PMID 35158933, 2022). "HRAS, NRAS, and KRAS, collectively referred to as oncogenic RAS, are the most frequently mutated driver proto‐oncogenes in cancer; the relationship between oncogenic RAS and ferroptosis is still controversial." (PMID 34878732, 2022). "After assessing the endogenous regulators of the AGO2–RAS interaction, we next asked if AGO2 played a functional role in promoting mutant HRAS and NRAS cancers." (PMID 35923912, 2022). "Several DEGs were identified that are differentially expressed between drug-sensitive and -resistant cancer cell lines (for pan-cancer NRAS-mutant cell lines) using Welch’s t-test (unequal group variance) with threshold p < 0.05, for 5 drugs." (PMID 35534592, 2022). "The mutational analysis highlighted the likely importance of NRAS, KRAS, JAK2, and CREBBP in pediatric cancer development because these genes are the most commonly mutated genes in pediatric cancer patients." (PMID 36497424, 2022). "These insights are expected to help improve pan-cancer drug sensitivity to these select drugs acting on the molecules involved in the NRAS signaling pathway, and will also be useful in drug repurposing studies utilizing our chosen targets." (PMID 35534592, 2022). "This study found that the NRAS mutation rate in patients with ECRC is 3.23%, which was similar to that of advanced cancer." (PMID 35837115, 2022). "Taken together, our study finds a novel role for AGO2 as a regulator of cellular proliferation and senescence in mutant HRAS and NRAS-driven cancers through an EGFR–AGO2–RAS signaling axis." (PMID 35923912, 2022). "Despite the evidence for a functional role of mutant KRAS–AGO2 interaction in cellular transformation and proliferation, the role of AGO2 in mutant HRAS or NRAS cancers is unclear." (PMID 35923912, 2022). "NRAS is the minor cancer-causing mutant among the three human RAS proteins, and approximately 2.3% of overall RAS mutations occur because of the NRAS mutant." (PMID 35409064, 2022). "Converging our above studies, we propose a working model of the mechanism of regulation of the select driver genes in pan-cancer (NRAS-mutant cancers) drug-resistance." (PMID 35534592, 2022). "Three RAS genes, HRAS, NRAS, and KRAS, are the most frequently mutated oncogenes in cancer, with the most paramount mutation being the KRAS mutation." (PMID 35281897, 2022).
cancer (continued). "Abnormal activation of Ras proteins (including RRAS2, MRas, HRas, KRas, and NRas) is the primary stimulus of oncogenes that has an essential role in the main signaling pathway in cancer." (PMID 36251702, 2022). "The three mammalian RAS genes (HRAS, NRAS and KRAS) encode four proteins that play central roles in cancer biology." (PMID 36393833, 2022). "RAS is the most common oncogene in cancer, and KRAS mutations are the predominant oncogene among the three RAS subtypes (HRAS, NRAS, and KRAS), which was regarded as “untreatable” targets for a long time." (PMID 35281897, 2022). "The prevalence of abnormal type 53BP1 expression and NRAS and TERT-p mutations in PDc was comparable to that of carcinomas." (PMID 35892838, 2022). "Here, we further our exploration of the utility of seriniquinone (SQ1) and its analogues (SQ2–SQ5) as agents that target cancer’s bearing point mutations on BRAF and NRAS genes." (PMID 34885944, 2021). "We investigated the regulatory interactions between circPVT1, let-7, and NRAS in A549 and HCT116 cells and functionalized the impact of circPVT1 expression on cancer hallmark phenotypes." (PMID 33907219, 2021). "RAS isoforms, including HRAS, NRAS and splice variants KRAS4A and KRAS4B, are some of the most frequently mutated proteins in cancer." (PMID 34222339, 2021). "Across a broad range of human cancers, gain-of-function mutations in RAS genes (HRAS, NRAS, and KRAS) lead to constitutive activity of oncoproteins responsible for tumorigenesis and cancer progression." (PMID 34607583, 2021). "Our findings on the proportion of all cancers with a RAS gene mutation are consistent with a recent analysis that performed a simpler weighted analysis of KRAS, NRAS, and HRAS mutations." (PMID 34645806, 2021). "For example, targeting the PI3k-Akt signaling pathway results in an anti-leukemic effect by activating oncogenes upstream (FLT3-ITD, KIT, NRAS, etc.); and dysregulated Ca2+ homeostasis plays a crucial role in the pathogenesis of various cancers." (PMID 33926391, 2021). "One trial assesses the safety and efficacy of ELI-002 immunotherapy, a novel amphiphile therapeutic vaccine targeting KRAS-driven cancers, for patients with KRAS or NRAS mutations (G12D or G12R) in various solid tumor types including GBC (NCT04853017)." (PMID 34771420, 2021). "Hyperactivation of the MEK1/2-ERK signaling axis due to mutations in NRAS and BRAF drives oncogenesis in ~30% of human cancers, and targeting RAF and MEK can be a curative therapy for these cancers." (PMID 34064422, 2021). "HRAS, NRAS and KRAS, collectively referred to as oncogenic RAS, are the most frequently mutated driver proto-oncogenes in cancer." (PMID 34485382, 2021). "In terms of cancer genes, SBS7 caused a large number of BRAF and NRAS mutations in SKCM, and SBS10 caused some high-frequency mutations in PTEN genes in UCEC." (PMID 34901014, 2021). "Cytoplasmic RP11-705C15.3 specifically binds to mature miR-145-5p and elevates NRAS, a critical target of miR-145-5p in cancers." (PMID 33311650, 2021). "In contrast, our integrated genomic-epidemiology approach provides a revised estimate of 15% of cancers harboring a KRAS, NRAS, or HRAS mutation – less than half of those previously reported estimates." (PMID 34645806, 2021). "HotPho successfully identifies likely functional mutational clusters and phosphosites in known cancer proteins, including EGFR, KIT, and KRAS/HRAS/NRAS, many of which are in kinase domains." (PMID 33875650, 2021). "This suggests that in particular cancers, for KRAS, BRAF, and NRAS, the major drivers of oncogenesis are gene mutations rather than cellular mRNA levels." (PMID 33398072, 2021).
cancer (continued). "RAS mutations (HRAS, NRAS, and KRAS) are among the most common oncogenes, and around 19% of patients with cancer harbor RAS mutations." (PMID 34301278, 2021). "Primary outcome measurement is enrichment of RAS (KRAS, NRAS and HRAS) alterations in BRAF variant cancers." (PMID 33507258, 2021). "KRAS is the most commonly mutated (86%), followed by NRAS (11%), and HRAS (3%) in RAS-driven human cancers." (PMID 34956887, 2021). "The most frequent mutated oncogene family in the history of human cancer is the RAS gene family, including NRAS, HRAS, and, most importantly, KRAS." (PMID 34638560, 2021). "The RAS family of oncogenes (HRAS, NRAS, and KRAS) are among the most frequently mutated protein families in cancers." (PMID 33924994, 2021). "This Ras-isoform dependent propensity to promote stemness strikingly correlates with the mutation frequency of RAS genes, with KRAS, NRAS and HRAS being mutated in 75%, 17% and 7% of RAS-mutant human cancers." (PMID 33544116, 2021). "Mutations in the NRAS gene can activate the RAS/MAPK signaling and have been reported to be associated with various cancers." (PMID 34063325, 2021). "Of these, the Ras pathway is the most significant pathway, Ras oncogenes are the most common oncogenes in human cancer, members of this superfamily of GTPases (KRAS, NRAS, and HRAS), which encode four highly conserved Ras proteins sharing 85% homology." (PMID 34513708, 2021). "Though preventing RAS from membrane association was the right approach, inhibiting farnesylation allowed for NRAS and KRAS mutant cancers to initiate alternative membrane association mechanisms, such as geranylgeranylation, another form of prenylation." (PMID 34830283, 2021). "The three RAS genes (HRAS, NRAS and KRAS), hereafter collectively referred to as oncogenic RAS, are the most frequently mutated driver proto-oncogenes in cancer, with KRAS being the most prevalent." (PMID 34485382, 2021). "Actually, NRAS is a very important gene involving many cancer-related signaling pathways, such as MAPK, mTOR, and PI3K-Akt signaling pathways." (PMID 33579226, 2021). "Next, we tested the PHASIFY method in 91 clinical plasma samples from 34 unique patients collected at different time points with diverse advanced cancers and BRAF, KRAS or NRAS mutations." (PMID 34608196, 2021). "Taken together, our results demonstrate that SIJ1795 and SIJ1772 are capable of inducing apoptosis and G0/G1 cell cycle arrest on Ba/F3 cells transformed with mtRAS (NRAS-G12D and NRAS-G12V), and cancer cells harboring mtRAS." (PMID 34956887, 2021). "Several studies have found that the WT allele corresponding to the specific mutated RAS gene (WT HRAS in HRAS-mutated cancers; WT NRAS in NRAS-mutated cancers; WT KRAS in KRAS-mutated cancers) suppresses tumorigenesis." (PMID 33924994, 2021). "Taken together, SIJ1795 and SIJ1772 block mtRAS downstream signaling (MAPK and PI3K/AKT pathways) in not only Ba/F3 cells transformed with mtRAS (NRAS-G12D and NRAS-G12V), but also cancer cells expressing mtRAS in a concentration dependent fashion." (PMID 34956887, 2021). "RAS oncogenes (HRAS, NRAS, and KRAS) are one of the most common mutated genes in human cancer with RAS activation occurring in around 30% of all cancers." (PMID 34644109, 2021).
cancer (continued). "The three RAS tissue specific isoforms (NRAS, neuroblastoma ras viral oncogene homolog; KRAS, Kirsten rat sarcoma viral oncogene homolog; HRAS, Harvey rat sarcoma viral oncogene homolog) are frequently mutated in cancers." (PMID 32850962, 2020). "In this study, the phenotypic effects on various cancer hallmarks of the novel NRAS mutant E132K, and the canonical NRAS mutants G12D and Q61K which remain poorly characterized, are described." (PMID 32620824, 2020). "Amongst the most common mutations across all cancers that also occurred in GBCs were KRAS G12/G13 (5 samples), PIK3CA H1047/E545/E542 (6 samples) and NRAS Q61 (1 sample)." (PMID 32839463, 2020). "Consistently, ZnAPC has been shown to downregulate NRAS mRNA and NRAS protein expression and induce cancer cell death upon photo-irradiation, even in the presence of an ROS scavenger, N-acetyl cysteine." (PMID 33198362, 2020). "The most significant KEGG pathway targeted and possibly downregulated by the most abundant sEV-contained miRNAs included several genes related to cancer progression such as NRAS." (PMID 32575666, 2020). "RAS proteins play a causal role in human cancer, and the widespread prevalence of RAS mutations (KRAS, NRAS, HRAS) in human cancer has been recognized for many years." (PMID 32100402, 2020). "Prioritizing cancer variants based on external databases, like COSMIC, rescued NRAS somatic mutations which were found at very low VAF in one sample in the reference PON." (PMID 33261552, 2020). "Despite not having significant effects on protein structure, the acidic to basic amino acid change in NRAS E132K was found to affect distinct cancer hallmarks." (PMID 32620824, 2020). "Mutations in the three major Ras isoforms, HRAS, NRAS, and KRAS, which impair GTPase activity and/or the ability of Ras to interact with negative regulators are found in approximately a third of human cancers." (PMID 31497244, 2019). "Altogether, the three human Ras genes, KRAS, NRAS, and HRAS, are among the most frequently mutated oncogenes in cancer, cumulatively estimated at 25–30% of all malignancies." (PMID 31712554, 2019). "Amplification of the oncogenes ERBB2, CDK6, MDM2 affected dependency, as did point mutations in PIK3CA, KRAS, NRAS, VHL and BRAF, validating our approach to highlight genes with significance in cancer." (PMID 30803482, 2019). "The proximal interactions of these SNAREs were assessed by a similar experimental design for KRAS, HRAS, and NRAS in cells derived from the most cancer-relevant tissues for each isoform." (PMID 31712554, 2019). "Encoded by the KRAS4A, KRAS4B, HRAS, and NRAS genes, RAS family members are among the most frequently altered oncogenes in human cancers." (PMID 31681559, 2019). "About one-third of all human cancers exhibit oncogenic mutations in RAS isoforms (KRAS, NRAS, and HRAS) making Ras an important anti-cancer target." (PMID 31856761, 2019). "The Ras/Raf/MEK/ERK1/2 pathway plays an essential role in human cancers and its contribution in leukemogenesis has been supported by a high incidence of mutations identified in the RAS gene family, such as NRAS and by inappropriate activation of the pathway." (PMID 31645898, 2019). "NRAS(p.Q61H) is one of the cancer COSMIC sites included in the kit and is used here as a negative control." (PMID 30866797, 2019). "Although KRAS, HRAS, and NRAS share functional similarities, KRAS missense gain-of-function mutations tend to occur on the 12th codon, while those in HRAS and NRAS occur on the 61st codon and are differentially utilized across cancer types." (PMID 31681559, 2019). "As expected, known cancer proteins BRAF, PIK3CA, KRas, Akt1, IDH1, and NRas showed the highest hotspot mutation scores in the TCGA dataset." (PMID 31345222, 2019). "Since patients with mutant NRAS tumors tend to be older, with a history of chronic ultraviolet (UV) exposure, their cancers are more challenging to treat successfully." (PMID 30999681, 2019).